PDK3 (pyruvate dehydrogenase kinase 3)
Diseases named in the same sentence as PDK3 in open-access papers (continued):
Sharing a sentence is not in itself a finding about the gene and the disease.
chronic hepatitis B (1 paper, 2024). "Consistent with our in vitro findings, in people with chronic hepatitis B there was significantly increased expression of PDK1, PDK2, and PDK3 compared to healthy liver, with a strong trend towards increased expression of LDHA (P =0.057)." (PMID 38655824, 2024).
endometriosis (1 paper, 2023). The growth of functional endometrial tissue in anatomic sites outside the uterine body. "Our results found that PDK3 was overexpressed in the eutopic endometrium in women with endometriosis." (PMID 36930359, 2023).
heart failure (1 paper, 2019). Inability of the heart to pump blood at an adequate rate to meet tissue metabolic requirements. "PDK3 expression was not measured due to low expression in the heart, whereas mRNA expression changes in PDK2 and PDK4 isoforms have been reported for human heart failure." (PMID 30881593, 2019).
leukemia (1 paper, 2021). A malignant (clonal) hematologic disorder, involving hematopoietic stem cells and characterized by the presence of primitive or atypical myeloid or lymphoid cells in the bone marrow and the blood. "Neo N termini (See Methods for definition) from leukemia-associated proteins such as PDK3 and LAT2 were elevated in relapse cases." (PMID 33722259, 2021).
Lewis lung carcinoma (1 paper, 2025). "To investigate the regulation of Pck1 and Pdk3 by IL-6 in vivo, we compared B6 mice injected with Lewis lung carcinoma (LLC) cells that were either engineered to express IL-6 or to lack IL-6 expression." (PMID 40275022, 2025).
lung adenocarcinoma (1 paper, 2023). A carcinoma that arises from the lung and is characterized by the presence of malignant glandular epithelial cells. "The amplified products were subjected to agarose gel electrophoresis, and six samples all gave clear bands in the correct region indicated by the marker, confirming that the six predicted six-HRGs (STC1, PFKL, HK1, PDK3, SLC2A1, XPNPEP1) were all expressed in lung adenocarcinoma A549 cells." (PMID 37576511, 2023).
metastatic melanoma (1 paper, 2021). A melanoma that has spread from its primary site to another anatomic site. "HIF-1/PDK3 bioenergetic pathway is validated to be a new target for therapeutic intervention in metastatic melanomas." (PMID 33739396, 2021). "In metastatic melanomas, HIF-1/PDK3 axis functions as a sensor for metabolic stress, regulating mitochondrial ROS level under normoxia." (PMID 33739396, 2021).
neuroblastoma (1 paper, 2020). Neuroblastoma (NB) is the most common solid, extracranial childhood tumor. "In contrast, all three shRNA vectors targeting PDK3 only reduced cell proliferation but did not induce neuron differentiation morphology, suggesting a critical role of PDK1 in regulating neuroblastoma cell differentiation." (PMID 32029721, 2020).
osteoporosis (1 paper, 2024). A condition of reduced bone mass, with decreased cortical thickness and a decrease in the number and size of the trabeculae of cancellous bone (but normal chemical composition), resulting in increased fracture incidence. "This will help to reveal the broader biological functions of Pdk3 in osteoporosis." (PMID 39399421, 2024).
osteosarcoma (1 paper, 2024). A usually aggressive malignant bone-forming mesenchymal neoplasm, predominantly affecting adolescents and young adults. "Expression profiles of C1QTNF1-AS1, miR-34a-5p, LDHA, and PDK3 in osteosarcoma cells were analyzed using RT-PCR and western blot analyses, revealing their intricate relationships." (PMID 39850812, 2024). "Suppressing the expression of LDHA and PDK3 in vivo can disrupt the metabolic pathways of osteosarcoma cells, thereby inhibiting their proliferation and invasiveness." (PMID 39850812, 2024). "The restoration or enhancement of miR-34a-5p function can effectively inhibit the proliferation and invasiveness of osteosarcoma cells, and by modulating the expression of enzymes such as LDHA and PDK3, the metabolic profile of osteosarcoma cells can be altered." (PMID 39850812, 2024). "Western blot analysis further confirmed this observation, demonstrating a significant decrease in the protein expression of PDK3 and LDHA in osteosarcoma cells due to the overexpression of miR-34a-5p." (PMID 39850812, 2024). "The qRT-PCR analysis results indicated that the expression levels of both PDK3 and LDHA were significantly downregulated in osteosarcoma cells following the overexpression of miR-34a-5p." (PMID 39850812, 2024).
Renal cyst (1 paper, 2024). A fluid filled sac in the kidney. "The upregulation of PDK1 (3.3×) and PDK3 (1.5×) in renal cysts suggests the inhibition of PDC activity, and therefore decreased conversion of pyruvate to acetyl-CoA for oxidative metabolism (bottom)." (PMID 39000280, 2024).
urinary bladder urothelial carcinoma (1 paper, 2021). "We investigated the role and prognostic value of PDK3 expression in patients with upper urinary tract urothelial carcinoma (UTUC) and urinary bladder urothelial carcinoma (UBUC)." (PMID 34589439, 2021).
urothelial carcinoma (1 paper, 2021). A malignant neoplasm derived from the transitional epithelium of the urinary tract (urinary bladder, ureter, urethra, or renal pelvis). "Correlations between PDK3 expression and other clinicopathological parameters in urothelial carcinomas." (PMID 34589439, 2021).
cancer (45 papers, 2010 to 2026). A tumor composed of atypical neoplastic, often pleomorphic cells that invade other tissues. "Altogether, our results support a conserved mechanism whereby IL-6–JAK–STAT signalling promotes hepatic PDK3 expression, contributing to mortality linked to cancer." (PMID 40275022, 2025). "PDK3 is a mitochondrial enzyme that is activated in various human cancers, causing them to progress." (PMID 36559012, 2022). "Upregulation of pyruvate dehydrogenase kinase (PDK) isoforms including PDK3 was reported in different cancers and associated with chemoresistance." (PMID 31638999, 2019). "Overexpression of PDK3 is associated with poor prognosis in a few cancers." (PMID 38400534, 2024). "Higher expression of PDK3 is associated with higher tumor stage in many cancers." (PMID 34589439, 2021). "Thus, PDK3 plays a key role in metabolic switch control during the progression of cancer and is implicated in cell survival coupled with hypoxia-induced metabolic switch." (PMID 32422877, 2020). "One putative splice site variant was found in PDK3, a gene that encodes an enzyme involved in the shift of energy production site from the mitochondria (oxidative phosphorylation) to the cytoplasm (glycolysis) reported in cancer cells." (PMID 28720891, 2017). "Thus, our findings suggest that the IL-6–JAK–STAT-signalling-dependent induction of hepatic Pdk3 expression represents a previously unknown pathogenic mechanism underlying metabolic disorder in cancer cachexia." (PMID 40275022, 2025). "Hence, hordenine itself or its derivatives may be exploited in the development of potent and selective PDK3 inhibitors for the clinical management of cancer and other PDK3 associated diseases." (PMID 32422877, 2020). "The prognostic model incorporates genes, such as YY2, PDHA1, SDC3, PPP2CB, and PDK3, all of which have been previously reported to influence cancer prognosis." (PMID 41235100, 2025). "The targets for HIF-1α include LDH-A, PFKFB3, PDK-1, and PDK-3; therefore, the expression and activities of these proteins are increased in cancer cells." (PMID 38339256, 2024). "Simultaneously, PDK3 plays a crucial role in cancers and has been regarded as a promising target for cancers." (PMID 36930359, 2023). "The potential importance of pyruvate dehydrogenase kinase 3 (PDK3) in metabolic cancer switching supports the idea of its role as a cancer therapy target." (PMID 33401572, 2021). "Similar to PDK1, PDK3 also participate in the metabolic switch of cancer cells, and has recently been considered as a potential pharmacological target for varying types of cancers." (PMID 33739396, 2021). "PDK3 plays an important role in the metabolic switch and drug resistance, and is potentially a novel target for cancer therapy." (PMID 33739396, 2021). "To investigate the predictive influence of PDK3 expression on cancer metastasis and patient survival in UC, we utilized univariate and multivariate analyses." (PMID 34589439, 2021). "All these studies validate PDK3 as a potential drug target for cancer therapy and support the development of therapeutic molecules against PDK3." (PMID 32422877, 2020). "Analysis of the eligible samples revealed that recurrent patients show high values for all the variables associated with the severity of cancer and exhibit high expression levels for ME3, PDK3, CHKA, and MALAT1 transcripts." (PMID 33375130, 2020). "For instance, HSF1 can drive the transcription of PDK3 (Pyruvate Dehydrogenase Kinase 3) to promote glycolysis in chemo-resistant cancer cells." (PMID 32838807, 2020). "Amongst all isoforms, the activity of PDK3 is determined by its robust binding to the L2 domain and its overexpression is related to the different types of cancers." (PMID 32422877, 2020). "The results of this study are in agreement with the previous studies, which also suggested that inhibition of PDK3 using synthetic or natural molecules leads to a decrease in cancer cell growth." (PMID 32422877, 2020).
cancer (continued). "The positive correlation between overexpression of PDK3 and metastatic progression suggests the importance of PDK3 as a drug target in cancer therapeutics." (PMID 32422877, 2020). "Many studies report overexpression of PDK3 in many cancers and a positive relationship of PDK3 expression was noticed with the cancer progression." (PMID 32422877, 2020). "PDK3 plays a pivotal role in this metabolic switching during the progression of cancer and is involved in cell survival and hypoxia-induced metabolic alterations thus highlighting its importance as a prominent target for cancer therapy." (PMID 32422877, 2020). "PDK3 is a member of the pyruvate dehydrogenase kinase (PDK) family that regulates the metabolic switch in cancer cells." (PMID 31409724, 2019). "PDKs have four isoforms and a significant up-regulation of PDK3 was seen in cancer in our RNA-Seq data." (PMID 31638999, 2019). "IDH2 and PDK3 have been shown to positively regulate the proliferation and tumorigenesis of various cancer cells." (PMID 29772705, 2018). "Because of the stronger inhibitory effect and its importance as an anti-cancer target, we searched for phenylbutyrate binding site on PDK3." (PMID 25601413, 2015). "Inhibition of PDK1 or PDK3 impairs cell growth and increases oxygen consumption in human cancer cell lines." (PMID 25601413, 2015). "This approach allowed us to reveal the conserved pathogenic role of Upd3–JAK–STAT or IL-6–JAK–STAT signalling in cancer-associated metabolic disorder, highlighting a potential therapeutic strategy of targeting hepatic gluconeogenesis or PDK3 in IL-6-driven cancer cachexia." (PMID 40275022, 2025). "For cancer targets, isocaryophyllene showed the highest potential as a ligand in the binding domains of pyruvate dehydrogenase kinase 3 (PDK3) (PDB ID: 1Y8O) and signal transducer and activator of transcription 3 (STAT3) (PDB ID: 6NJS), with glide scores of −6.4 and −6.0 kcal/mol, respectively." (PMID 41226145, 2025). "Similarly, HSF1 promotes expression of pyruvate dehydrogenase kinase 3 (PDK3), which enhances glycolysis and analogically supports cancer progression and resistance." (PMID 40287736, 2025). "Increased expression of these genes in fly, mouse, and human correlates with poor prognosis, and hepatic expression of Pdk3 emerges as a previously unknown mechanism contributing to metabolic dysfunction in cancer cachexia." (PMID 40275022, 2025). "Previous studies have confirmed that PDK3 overexpression enhances cancer cell proliferation." (PMID 38429830, 2024). "PDK3 belongs to PDK family regulating cancer cell metabolic switches." (PMID 38429830, 2024). "PDK3 drew our attention because of its increasing importance in cancer metabolism." (PMID 36369467, 2022). "Pyruvate dehydrogenase kinase 3 (PDK3) could alter glucose metabolism in cancer by inactivating pyruvate dehydrogenase kinase and overexpression of PDK is related to tumor invasion, metastasis, and drug resistance." (PMID 33494814, 2021). "In addition, an increase in cellular oxidative stress has been reported when PDK3 was inhibited in cancer cells." (PMID 34586189, 2021). "The overexpression of PDK3 correlates with cancer progression." (PMID 33401572, 2021). "Finally, our study suggested that hordenine is a potential inhibitor of PDK3 with a promising anti-cancer use." (PMID 32422877, 2020). "Because PDK3 is an important regulator of glycolysis, which is hyper-activated in cancer development, we examined whether miR-497-5p directly regulated PDK3 in GC cells." (PMID 31409724, 2019). "Therefore, NAC1/PDK3 axis can guarantee cancer cells continuously shutdown of mitochondrial respiration when face hypoxic stress." (PMID 29163184, 2017). "Based on our present data, ART-induced over-expression of PDK3 may be a new mode of anti-cancer activity of ART." (PMID 20428086, 2010).
cancer (continued). "PDK3 may represent the critical molecule that controls the metabolic switch of cancer cells from oxidative phosphorylation to aerobic glycolysis (Warburg effect)." (PMID 20428086, 2010). "Our data suggest that PDK3 could be a potential therapeutic target for cancer cachexia treatment." (PMID 40275022, 2025). "Furthermore, PDK3 has emerged as a key regulator of metabolism and is upregulated in many cancers." (PMID 38400534, 2024). "The activation or intensification of cancer cells' mitochondrial metabolism through hypoxia-inducible factor-1 α (HIF-1 α) and pyruvate dehydrogenase kinase-3 (PDK) (by nuclear accumbens-1 and dichloroacetate (DCA)) reduce the glycolysis of cancer cells." (PMID 37864163, 2023). "PDK1, PDK2, and PDK3 play a role of tumor promoters, while PDK4 plays a different role in tumor aggressiveness depending on the cancer origin." (PMID 36474273, 2022). "PDK1, PDK2, PDK3, PDK4, PDP2, and PDPR genes can regulate the glucose metabolism and glycolysis of cancer cells." (PMID 34199666, 2021). "Regarding cancer cell defense mechanism, it has been shown that HSF1 forms a positive feedback loop with pyruvate dehydrogenase 3 (PDK3) to drive chemoresistance of cancers." (PMID 31878360, 2019). "Therefore, PDK1 and PDK3 inhibition by phenylbutyrate might be therapeutically effective in cancer." (PMID 25601413, 2015). "The pyruvate dehydrogenase kinase 3 gene is another target for HSF1, which inhibits the conversion of glucose to Acetyl CoA by inactivating the pyruvate dehydrogenase complex, thus ensuring the continuation of glycolysis in cancer cells." (PMID 35990198, 2022). "In hypoxia and cancer, HIF1α activates the expression of PDK1 and PDK3." (PMID 33739396, 2021). "However, the correlations among the levels of PDK3 and EEF1A1, cell apoptosis, and cancer progression in UC require further analysis." (PMID 34589439, 2021). "To assess whether the hepatic Pdk3 upregulation we observed in the CACS KL and LLC+IL-6 mice is a universal phenomenon or specific to only these models, we analysed liver Pdk3 expression in other mouse cancer models." (PMID 40275022, 2025). "Indeed, in this study we demonstrated that silencing of NAC1 expression promoted mitochondrial respiration and increased vulnerability to cell death in hypoxia, and survival advantage was reversed when PDK3 was over-expressed in NAC1 absent cancer cells." (PMID 29163184, 2017). "The mRNA levels of three out of six genes we tested (SLC2A3, GPI, and PDK3) were selectively decreased by PRDX2 and PRDX4 during prolonged hypoxia, suggesting that PRDX2 and PRDX4 may be negative regulators of glucose reprogramming in cancer cells exposed to prolonged hypoxia." (PMID 26837221, 2016). "The results of this study were consistent with these findings, as NAC1-overexpressed cancer cells would result in the accumulation of pyruvate in hypoxia, and NAC1 can induce PDK3 but not PDK-1, -2, or -4 expression in hypoxia." (PMID 29163184, 2017). "Overexpression of PDK3 could reduce oxygen consumption and excessive ROS production in hypoxic NAC1 absent cancer cells, whereas increase glucose uptake in vivo." (PMID 29163184, 2017). "To determine whether PDK3 down-regulation mediated ROS production in cancer cells with absence of NAC1 contribute to hypoxia-induced apoptosis, we transfected a Flag-PDK3 plasmid into HeLa cells with silencing of NAC1 expression." (PMID 29163184, 2017).